HSD17B6 (hydroxysteroid 17-beta dehydrogenase 6)
Description:
NAD-dependent oxidoreductase with broad substrate specificity that shows both oxidative and reductive activity (in vitro). Has 17-beta-hydroxysteroid dehydrogenase activity towards various steroids (in vitro). Converts 5-alpha-androstan-3-alpha,17-beta-diol to androsterone and estradiol to estrone (in vitro). Has 3-alpha-hydroxysteroid dehydrogenase activity towards androsterone (in vitro). Has retinol dehydrogenase activity towards all-trans-retinol (in vitro). Can convert androsterone to epi-androsterone. Androsterone is first oxidized to 5-alpha-androstane-3,17-dione and then reduced to epi-andosterone. Can act on both C-19 and C-21 3-alpha-hydroxysteroids.
Synonyms: RODH; SDR9C6; HSE
Tractability: Antibody: UniProt places it where antibodies can reach, with high confidence; UniProt predicts a signal peptide or a membrane-spanning region. PROTAC: ubiquitination databases record sites on it; its protein half-life has been measured.
Gene: Protein-coding gene on chromosome 12 (56,751,817 to 56,788,409, forward strand). Ensembl gene ENSG00000025423.
Subcellular location: Microsome membrane; Early endosome membrane
Subcellular location (Human Protein Atlas): Nucleoplasm; Vesicles
Pathways (Reactome):
Sensory Perception: The canonical retinoid cycle in rods (twilight vision)
Gene Ontology:
Molecular function: 5-alpha-androstane-3-beta,17-beta-diol dehydrogenase (NADP+) activity; all-trans-retinol dehydrogenase (NAD+) activity; androstan-3-alpha,17-beta-diol dehydrogenase (NAD+) activity; androsterone dehydrogenase [NAD(P)+] activity; catalytic activity; electron transfer activity; estradiol 17-beta-dehydrogenase [NAD(P)+] activity; oxidoreductase activity; testosterone dehydrogenase (NAD+) activity; alcohol dehydrogenase (NAD+) activity; oxidoreductase activity, acting on the CH-OH group of donors, NAD or NADP as acceptor; testosterone dehydrogenase (NADP+) activity
Biological process: brexanolone catabolic process; androgen biosynthetic process; androgen catabolic process; retinol metabolic process; estrogen biosynthetic process
Cellular component: early endosome membrane; endoplasmic reticulum
Genetic constraint (gnomAD): Loss-of-function variants: 15 observed, 27.85 expected, observed/expected ratio (o/e) 0.54, 90% interval 0.36 to 0.83. The upper end of that interval is the gene's LOEUF score, 0.83, which puts it in group 3 of 6, group 1 being the genes least tolerant of losing a copy. Missense variants: 357 observed, 404.95 expected, observed/expected ratio (o/e) 0.88, 90% interval 0.81 to 0.96. Synonymous variants: 138 observed, 160.68 expected, observed/expected ratio (o/e) 0.86, 90% interval 0.75 to 0.99.
Homologues: Orthologues: macaque HSD17B6 (93% identical), pig HSD17B6 (81% identical), dog HSD17B6 (80% identical), mouse Hsd17b6 (73% identical), rat Hsd17b6 (71% identical). Paralogues in human: RDH16 (66% identical), SDR9C7 (50% identical), RDH5 (50% identical), DHRS9 (45% identical), BDH1 (39% identical), HSD11B2 (32% identical), HSD17B2 (31% identical), SDR16C5 (26% identical), RDH10 (25% identical), RDH12 (25% identical), RDH11 (25% identical), HSD17B1 (24% identical), and 13 more.